TF (transferrin)
Diseases named in the same sentence as TF in open-access papers (continued):
Sharing a sentence is not in itself a finding about the gene and the disease.
cancer (continued). "Targeted cancer therapy can employ specific receptors and transporters, such as riboflavin, glucose, transferrin, etc., which are highly overexpressed on some cancer cells’ surfaces." (PMID 37511405, 2023). "Transferrin is responsible for the extracellular transport of iron to actively dividing cells, including cancer cells." (PMID 37505047, 2023). "Similarly, the reduction of iron delivery by transferrin and the inhibition of associated metabolic processes, including the functioning of transferrin receptors, are considered important targets for the design and development of new potential pharmaceuticals against microbial infections and cancer." (PMID 37513928, 2023). "Targeted staining of specific cancer cells using CDs typically relies on the attachment of special ligands, such as transferrin, folic acid, and hyaluronic acid." (PMID 37947732, 2023). "Drug delivery systems using transferrin-mediated liposome targeting show promise for cancer therapy." (PMID 37893242, 2023). "For now, it is notable that a minor distortion of the ‘gradual atavism’ in the invasive/non-invasive cancer cells (the fold increase in 10–17 phylostrata compared with 7–9 phylostrata) cannot be explained by the higher expression of TF ZF-C2H2." (PMID 37047167, 2023). "The most reported coagulation proteins involved in cancer progression include TF, TF-FVII, thrombin, and fibrin." (PMID 37046617, 2023). "Based on this premise, here, we synthesized VCR-loaded pluronic-coated iron oxide nanoparticles consisting of FA and TF as dual ligands (VCR-PMNP-FA-TF) for targeted delivery, sustained release and combinatorial chemo-hyperthermia therapy for cancer cells." (PMID 38102193, 2023). "This process of non-transferrin-mediated iron uptake, involving Lcn-2 as a key player, has been shown to be involved in cancer progression." (PMID 37958332, 2023). "These transferrin-bearing, zein-based hybrid lipid nanoparticles efficiently entrapped docetaxel, leading to increased uptake by PC-3 and LNCaP cancer cells and significantly enhancing anti-proliferative efficacy at docetaxel concentrations exceeding 1 μg/mL." (PMID 38004621, 2023). "For instance, KRAS has been implicated in driving an aberrant overexpression of TF, as well as in promoting TF release as active cargo of cancer-derived extracellular vesicles (EVs)." (PMID 38188342, 2023). "Recently the scientist fabricated an immunosensor to detect transferrin levels indirectly in cancer patients." (PMID 37397018, 2023). "One of the most important and unique properties of L1 not found in any other drugs is the ability to remove iron from the iron transport protein transferrin found in blood, which delivers iron to all the cells of the body, including microbial and cancer cells." (PMID 37513928, 2023). "Galectin-3 interacts with TF-antigen on the surface of the transmembrane mucin protein MUC-1 in cancer cells." (PMID 36873388, 2023). "On the other hand, there was a downregulation of TF (coding for iron-binding factor) and VGF, a neuropeptide precursor implicated in cancer progression and metastasis." (PMID 37834191, 2023). "Another strategy to include extracellular materials is receptor-mediated endocytosis which allows cancer cells to incorporate cholesterol and transferrin, which is used to uptake iron." (PMID 36769044, 2023). "Mouse models and experimental therapeutics have demonstrated crucial roles for TF initiated cell signaling in the pathogenesis of cancer." (PMID 38028589, 2023). "In this sense, we designed transferrin (Tf)-conjugated PLGA nanoparticles (NPs) containing an organoselenium compound as an alternative to enhance the efficacy of cancer therapy and sensitize MDR tumor cells." (PMID 37630891, 2023). "Elevated plasma iron, especially in the form of transferrin iron, supports cell-proliferative diseases including infection and cancer." (PMID 36978919, 2023).
cancer (continued). "They interact with cell adhesion molecules (CAMs) such as cadherins, catenins, integrins and TF antigens to induce signals for cancer cell migration and metastasis." (PMID 37444377, 2023). "Many of the glycosylation changes in cancer are known to lead to the appearance of short oncofetal carbohydrate structures such as TF, Tn and sialyl-Tn antigens." (PMID 37612278, 2023). "Transferrin and folic acid are both very effective ligands in targeted medicine and both of them are highly expressed in cancer cells." (PMID 38102193, 2023). "When MUC1 is overexpressed in cancer along with the TF antigen, the smaller CAMs are exposed, which enhances the motility of the cancer cells and helps them migrate through the basement membrane." (PMID 37444377, 2023). "Iron uptake in cancer cells is increased through the upregulation of Transferrin/Transferrin-receptor (Tf/TfR), and Lipocalin-2/Lipocalin-2 Receptor (Lcn-2/Lcn-2R) systems and also Divalent Metal Transporter-1 (DMT1)." (PMID 36986466, 2023). "Currently, the widely investigated formulations that often are composed of ligand-targeted components facilitate the binding to EGFR, PSMA, transferrin, folate receptors, etc., but most human cancers still cannot be imaged." (PMID 37151801, 2023). "When we focus on the most severe cancer stages (Iva, IVb and IVc), only albumin and transferrin had a significant difference, decreasing as the severity of the cancer stage increases." (PMID 36771369, 2023). "It plays an essential role in iron homeostasis thought the conversion of ferrous iron Fe2+ to ferric iron Fe3+ which is internalized by cells via TF and therefore regulates ferroptosis in cancer cells." (PMID 38006431, 2023). "Binding of galectin-3 to TF/MUC1 on cancer cells also increases cancer cell-cell homotypic aggregation and survival in the blood circulation." (PMID 37612278, 2023). "It has been described that there are some receptors overexpressed in cancer cells, including transferrin, integrin, folate, EGFR, CD13, monocarboxylate transporter-1 and biotin." (PMID 37284445, 2023). "Ionic mimicry (similar ionic charge/ionic radius ratios) allows Ru to compete with Fe for binding with biomolecules, employing the transferrin pathway to specifically target cancer cells." (PMID 36838947, 2023). "Upon exposure to TNFα, cancer cells increase their expression of TF and produce TF‐bearing microparticles with potent local pro‐coagulant effects." (PMID 37795779, 2023). "Previous studies have demonstrated that EMT drives TF expression in vitro in different carcinoma models." (PMID 38201433, 2023). "TWIST is another TF that acts as a predominant regulator of EMT and is associated with cancer stem cell phenotyping." (PMID 36431925, 2022). "Iron binds to transferrin (iron transporter protein) and forms holo-transferrin, which binds to the transferrin receptor and is internalized into cancer cells through receptor-mediated endocytosis." (PMID 35267408, 2022). "TF, a transmembrane glycoprotein well known for its role in the extrinsic coagulation pathway has also been found to be overexpressed in several cancers, and therefore an appealing target for anti-cancer drug development." (PMID 36046842, 2022). "The upregulation of TF SIM2 stimulates the activity of downstream oncogene FOXM1 to construct an appropriate microenvironment for cancer cell metastasis through the secretion of exosomes from the malfunction of metabolism." (PMID 35164166, 2022). "The thematic analysis revealed four themes: transferrin/transferrin receptor-mediated drug delivery to the brain, cancer cells, gene therapy, nanoparticles, and liposomes as drug delivery systems." (PMID 36559067, 2022). "A systematic review reported the predictive ability of PA for nutritional status in advanced cancer patients and found that low PA was related to worse nutritional status as assessed by BMI, serum albumin level, transferrin, and fat-free mass." (PMID 36615707, 2022).
cancer (continued). "The activation of conduction factor CERK indirectly triggers dysregulation of the immune response, cancer cell proliferation, and metastasis by upregulating TF MYBL2 to overexpress." (PMID 35164166, 2022). "Drug interactions with transferrin and the control of iron delivery to cancer cells is another major target for anticancer drug design involving all cancer stages including initiation, proliferation and angiogenesis." (PMID 36430469, 2022). "With additional colorimetric property, this method also provides a visual indicator for abnormal health conditions with extreme transferrin statuses such as those found in cancers." (PMID 36140091, 2022). "Through direct drug-induced damage to the endothelium and by indirectly increasing the expression of TF procoagulant activity of monocytes and macrophages, chemotherapy poses a serious risk of increasing VTE within a cancer patient." (PMID 36552961, 2022). "At the early stages of cancer development, individuals with reduced transferrin values represented the majority among those with FID + CRA (60%)." (PMID 36555993, 2022). "Inflammatory cytokines produced in cancer patients lead to the upregulation of hepcidin, a protein that blocks the release of iron to transferrin (iron transporter)." (PMID 34979978, 2022). "RTPs, such as prealbumin, transferrin, and retinol-binding protein are important for the assessment of nutritional status in cancer patients." (PMID 35244810, 2022). "Thirdly, only one plasma sample from a cancer-free female was included in the analysis of the ratio of holo- and apo- forms of transferrin." (PMID 36555993, 2022). "The Tf-Ga disturbs the normal uptaking of the transferrin-iron complex, which leads to iron deprivation in cancer cells." (PMID 35564180, 2022). "Prospective trials with cancer incidence rates similar to the general population of women with a pelvic mass are need in order to determine if transferrin has added value to the dual marker combination of HE4 and CA125." (PMID 35267599, 2022). "Using pan-cancer data, a more in-depth examination of TF-miRNA modulation showed 26 dysregulated FFLs across 13 different types of cancer, as well as anticipated potential genes and therapeutic targets." (PMID 36483029, 2022). "Nucleic acids conjugated with polycations and crosslinked with transferrin can be used for the delivery of therapeutic genes to cancer cells." (PMID 36559067, 2022). "Artemisinin and its analogs enhance cancer cell delivery through human serum transferrin adducts and exert distinct anticancer effects on tumors with few side effects on normal cells." (PMID 33650320, 2021). "Transferrin is another type of ligand that can be used to target cancer cells with overexpression of transferrin receptors." (PMID 33498885, 2021). "The authors determined that the basis for homotypic recognition included the cell surface expression of the TF-antigen and E-cadherin, which were present on both the 4T biomimetic construct and the 4T1 parent cancer cells from which they were derived." (PMID 34070233, 2021). "Given TF’s ability to drive cancer cell growth and spread, therapeutic targeting of TF is an actively pursued area." (PMID 34395257, 2021). "Polyclonal antibody of transferrin (anti-TF) was immobilized on the electrode to indirectly detect cancer cells by detecting the binding of anti-TF to different types of transferrin through the Fe adhesion cycle between the transferrin and its receptor." (PMID 34360949, 2021). "Downregulation of TF is capable of inducing apoptosis and impairs cell survival of tumor cells, leading it to be a potential target for cancer therapy." (PMID 34203870, 2021).
cancer (continued). "The novel small molecule nanodrug candidate 2b with dual targeting acts through the EPR effect and TF/TFR interaction in A549 cancer cells and LLC tumors in C57/BL6 mice." (PMID 33892746, 2021). "This need is reflected by cancer cells having a higher expression of the TfR1 on their membranes, allowing the greater uptake of transferrin-bound iron from the bloodstream." (PMID 34572031, 2021). "The specific interaction between the TF antigen and surface galactin-3 facilitates cancer cell–cell adhesion, to vascular endothelial cells and to the ECM (fibronectin, collagen, and laminin, etc.)." (PMID 34070233, 2021). "Preoperarive low transferrin was associated with shorter relapse‐free survival (P < .001), overall survival (P < .001), and cancer‐specific survival (P = .004) compared with normal transferrin." (PMID 33860145, 2021). "Several parameters were assessed regarding the TF expression in CRC tumors: the percentage of labeled cancer cells, intensity of the staining, and the subcellular localization." (PMID 33572915, 2021). "Transferrin can facilitate the nanoparticle entrance to the cancer cells through receptor-mediated endocytosis pathway." (PMID 33498885, 2021). "As anticancer antibodies are quite expensive, many researchers investigated alternative ligand-based QDs including folic acid (FA), epidermal growth factors, transferrin, and a few aptamers to target cancer cells." (PMID 34745974, 2021). "Previous reports have shown higher sensitivity to natural killer (NK) cells towards human carcinoma cell lines expressing the TF antigen." (PMID 33572915, 2021). "In future, transferrin targeted drug delivery NPs can be used for treatment of other cancers as well." (PMID 33329007, 2020). "Transferrin (Tf) is a protein which has been used for targeted gene therapy, given that most cancer cells of lung carcinoma overexpress transferrin receptors." (PMID 33381459, 2020). "Ricin, gelonin and saporin have been conjugated to both transferrin and monoclonal antibodies against the human transferrin receptor and tested in different cancer settings." (PMID 32957689, 2020). "The TF genes interacting with each other and forming a subnetwork with immune and cancer-related genes that they regulate were involved in immune response." (PMID 32346613, 2020). "Multiple studies have reported the importance of mAbs in cancer; for example, an anti-mouse transferrin antibody fused with the GDNF (cTfRmAb-GDNF) can be delivered to the brain in vivo." (PMID 32957732, 2020). "The Thomsen–Freidenreich (TF) antigen and its biosynthetic precursor, Tn antigen, are often aberrantly glycosylated in cancer cells." (PMID 32992445, 2020). "Peptide T7 (His-Ala-Ile-Tyr-Pro-Arg-His) specifically targets brain endothelial and cancer cells overexpressing transferrin (Tf) receptors." (PMID 33007959, 2020). "Typically, the TF-induced EGFR activation is closely correlated with the procoagulant activity of cancer cells, which is achieved through the Nuclear transcription factor activates protein-1 (AP-1) transcriptional activation." (PMID 33243184, 2020). "For instance, TF (tissue factor) is a multifunctional membrane protein which correlates with various advanced cancers." (PMID 33665205, 2020). "Iron overload and transferrin iron saturation favors the proliferation of infections and cancer cells." (PMID 32545424, 2020). "Blockade of GM-CSF or inhibition of Jak kinases inhibits neutrophil transferrin expression and disrupted the paracrine loop between metastatic cancer cells and neutrophils, resulting in reduced metastasis." (PMID 33679721, 2020). "Although significantly burdened sites were identified for all cancer types analyzed, certain cancer types contained disproportionate numbers of burdened promoter/TF sites." (PMID 33092526, 2020). "Transferrin synthesis acts as an autocrine mechanism supporting iron supply and growth of cancer cells." (PMID 33679721, 2020).
cancer (continued). "Both plant and bacterial toxins have been chemically conjugated or fused through DNA cloning to transferrin or to anti-transferrin receptor antibodies to deliver toxic payloads to cancer cells." (PMID 32957689, 2020). "Transferrin, a kind of iron containing proteins, has been used as nanocarriers to directly deliver ARTs for cancer therapy in several cases." (PMID 32626687, 2020). "For example, in a recent study, Xing's group reported a system for pH-triggered cancer chemotherapy by coating graphene oxide (GO) with both transferrin and DHA, where transferrin served as not only a cancer cell-targeting ligand but also an iron carrier." (PMID 32626687, 2020). "Growth factor receptors, such as folate (FA) and transferrin (Tf) receptors, are regularly probed cancer cell targets owing to their overexpression in cancers of different histological origin." (PMID 33202648, 2020). "A particular attractive strategy in the quest to design novel anticancer agents is to target transcription factors PPIs, as TF operate at junction points in most oncogenic signalling pathways and are often functionally altered in many cancers." (PMID 32477463, 2020). "In 4T1 breast carcinoma, transferrin, an iron-transporting protein secreted by neutrophils, binds to its receptor expressed on cancer cells." (PMID 31474975, 2019). "The use of transferrin as a targeting agent is common, both for the management of anti-cancer drugs alone, for proteins with toxic effects and for nucleic acids." (PMID 31835393, 2019). "The conjugation of transferrin to liposomes increased the antiproliferative activity of plumbagin in the three tested cancer cell lines." (PMID 31341642, 2019). "The NDA135b was designed to carry transferrin as a targeting structure to facilitate the uptake of the particle by cancer cells expressing transferrin receptor and decrease the uptake by normal cells including phagocytes." (PMID 31181619, 2019). "These liposomes will be conjugated to transferrin (Tf), whose receptors are overexpressed on many cancer cells." (PMID 31341642, 2019). "For example, cancer cells frequently upregulate transferrin (increasing uptake of iron) and down regulate ferroportin (decreasing efflux of intracellular iron)." (PMID 31366108, 2019). "Rapidly dividing cancer cells are in a great need for iron so the increased expression of transferrin (iron-binding protein) receptors, TfR1-2 is reported for brain, lung, bladder, intestine, pancreas, and some other cancers." (PMID 30634580, 2019). "Contrary to above passive route, greater selectivity and specificity for cancer cells is achieved surface modification of NPs with ligands like transferrin, folic acid and antibodies for specific targeted therapy on glycan surface of the tumor cells." (PMID 31661003, 2019). "The uptake kinetics and pathway of riboflavin internalization in cancer cells compared to healthy cells was determined by co-localization studies using the well-established endocytosis marker transferrin." (PMID 30787877, 2019). "Transferrin‐bearing liposomes entrapping plumbagin are therefore highly promising therapeutic systems that should be further optimized as a therapeutic tool for cancer treatment." (PMID 31341642, 2019). "The glycoprotein transferrin was selected as a ligand because it is upregulated on the surface of cancer cells." (PMID 31752417, 2019). "The peritoneal lavage is rich in macrophages (in our samples, 45%–50% of leukocytes) that easily engulf nanoparticles and, thus, they are an important cell population to evaluate the cancer cell-targeting effectivity of transferrin adsorbed to NDA135b surface." (PMID 31181619, 2019). "The affinity of transferrin to the surface of cancer cells is 10–100 times greater than that of normal cells." (PMID 29996877, 2018). "Two groups of cancer-bearing mice were used: one treated with i. v. injection of transferrin and the other treated with apotransferrin." (PMID 30202000, 2018).